APOE (apolipoprotein E)
Diseases named in the same sentence as APOE in open-access papers (continued):
Sharing a sentence is not in itself a finding about the gene and the disease.
atherosclerosis (continued). "Additionally, in the in vivo study using Ang II-infused atherosclerosis-prone apolipoprotein E knockout mice, sRAGE significantly decreased the Evans blue-positive areas compared to those in the Ang II-infused or the saline-infused group, effectively maintaining the integrity of cell–cell contacts." (PMID 31562296, 2019). "Analysis of mRNA from ApoE−/− mice indicates T-cells within atherosclerotic lesions show the preferential expression of a limited number of TCR-variable gene segments suggesting that a limited set of antigens are responsible for the specific T-cell response present in atherosclerosis." (PMID 31849973, 2019). "In this study, we analysed atherosclerosis in Western diet (WD)-fed Sphk1−/− mice and Sphk2−/− mice, both with an ApoE-deficient background and found that Sphk2−/− mice, but not Sphk1−/− mice, show aggravation of atherosclerosis because of defective autophagic breakdown of LDs in macrophages." (PMID 31797978, 2019). "Therefore, Irisin and BAIBA might be involved in exercise-induced atherosclerosis suppression in humans in the same manner as in ApoE-KO/PGC-1α mice." (PMID 30858489, 2019). "Given that TLR4 is closely related to atherosclerosis, we hypothesized herein that caprylic acid (C8:0) would suppress inflammation via TLR4/NF-κB signaling and further promote the amelioration of atherosclerosis in apoE- deficient (apoE−/−) mice." (PMID 31182969, 2019). "Similarly, expressing human apoA-IV in the intestine of apoE-deficient background (apoA-IV/E0 mice) protected the mice from atherosclerosis without an increase in HDL cholesterol." (PMID 30959835, 2019). "In the model group (ApoE KO mice fed with high-fat diet for 8 weeks), atherosclerosis lesions, lumen blocking, disorder of smooth muscle, formation and accumulation of many foam cells, large number of inflammatory cells, and atherosclerosis plate-cholesterol clefts were detected." (PMID 30669336, 2019). "Indeed, SOD1 overexpression alone may increase the extent of atherosclerosis; however, overexpression of catalase, in addition to SOD1, reduces atherosclerosis in ApoE−/− mice." (PMID 31354915, 2019). "Thus, it can be concluded that a decrease in APOE serum level and its redistribution among lipoprotein classes in ε2 carriers observed with eGFR decline can promote the progression of lipid disturbances and accelerate atherosclerosis development." (PMID 30851738, 2019). "Thus, for example, lack of CD55 or CD59 in atherosclerosis-susceptible ApoE−/− mice, resulted in worse disease, while CD59 administration reduced the severity of experimental atherosclerosis by abrogating MAC formation." (PMID 31555668, 2019). "Indeed, PF4 or CD40L genetic deletion protects ApoE−/− mice from atherosclerosis." (PMID 31572732, 2019). "Therefore, ApoE−/− mice have been used to develop new drugs against atherosclerosis." (PMID 31817202, 2019). "Interestingly, it was found that Apolipoprotein E (ApoE) knockout mice developed remarkable hyperlipedimia, atherosclerosis and hearing impairment, which might share the similar pathogenesis of OSBPL2 deficit in SNHL48." (PMID 31427568, 2019). "Thus, ApoE−/− mouse is an excellent surrogate model to study atherosclerosis." (PMID 31429763, 2019). "Thus, the apoE−/− model promotes atherosclerosis by both lipid- and inflammation-mediated pathways." (PMID 30754681, 2019). "However, considering the deficiency of apoE genes, apoE−/− mice are unlikely to self-heal upon feeding a caloric restriction diet and do not exhibit the regression of atherosclerosis." (PMID 30958112, 2019). "To assess this hypothesis, we employed the ApoE−/− model of hyperlipidemia/atherosclerosis." (PMID 30483256, 2018). "Therefore, monitoring apoE-relevant microRNA signatures may provide new biomarkers for early atherosclerosis detection." (PMID 29789495, 2018). "Thus, we explored whether FGF21 was involved in the pathogenesis of atherosclerosis in apoE−/− mice." (PMID 30157856, 2018).
atherosclerosis (continued). "Atherosclerosis-prone ApoE−/− mice may develop dyslipidemia with subsequent accumulation of cholesterol ester-enriched particles in the blood, which not only induces a chronic inflammatory reaction in the vessels but also promotes the development of atherosclerotic plaques." (PMID 30041636, 2018). "Therefore, we set out to determine the effect of inulin on the development of atherosclerosis in hypercholesterolemic APOE*3-Leiden.CETP (E3L.CETP) mice, a model that is characterized by a human-like lipoprotein metabolism and that is susceptible to the development of atherosclerosis." (PMID 30409998, 2018). "However, mouse studies show that IL-6 depletion in ApoE-/- mice promotes atherosclerosis." (PMID 30013482, 2018). "Furthermore, the use of mimics and antagonists of apoE-relevant microRNA delivered via nanoparticles including liposomes and exosomes, could offer new therapeutic approaches to control atherosclerosis cardiovascular diseases." (PMID 29789495, 2018). "Finally, more recent evidence suggests that apoE may control the release of microvesicles that could modulate cellular signaling, inflammation and atherosclerosis at a distance." (PMID 29789495, 2018). "In the current work, we constructed two lentiviral vectors to knock down Lp-PLA2 and YKL-40 following collar-induced atherosclerosis in apoE-/- mice and elucidate whether selective or combined knockdown of the Lp-PLA2 and YKL-40 genes may ameliorate atherosclerotic plaques in apoE-/- mice." (PMID 30138439, 2018). "Thus, an general ApoE knock out (ApoE−/−) mouse model, which is a canonical mouse model for researches on atherosclerosis, hypercholesterolemia, hyperlipidemia and lipid metabolism, will also allow the study of the clinical relevance of ECM reprogramming during tumor progression." (PMID 29458390, 2018). "Thus, these ApoE−/− pigs could be valuable large animal models for providing further insight into translational studies of atherosclerosis." (PMID 30305304, 2018). "Our data revealed that apoE KO mice exhibited unique features of the gut microbiota diversity and compositions and these features may provide novel insight into understanding the relationship between gut microbiota and atherosclerosis." (PMID 30021609, 2018). "Given the fact that the gut microbiota plays an important role in many metabolic diseases such as obesity, diabetes, metabolic syndrome and atherosclerosis, we envisioned that the gut microbiota may be altered in apoE KO mice when challenged with a Western diet." (PMID 30021609, 2018). "Thus, the diversity of cytokines generated within the arterial wall may impact the protective potential of apoE on atherosclerosis development." (PMID 29789495, 2018). "Indeed, in contrast to apoE deficiency, the deficiency of apoA-I does not cause atherosclerosis in mice by itself." (PMID 30282955, 2018). "Thus, with the aim of elucidating the effects of hepatic Plpp3 deletion on circulating lipid levels, which might affect atherosclerosis development, a lipidomic analysis was conducted on Plpp3f/f apoE−/− Alb-Cre− and Plpp3f/f apoE−/− Alb-Cre+ mouse plasma." (PMID 28291223, 2017).
atherosclerosis (continued). "In the same way, it was reported that deficiency of the endogenously produced IL-33 and its receptor ST2 did not impact the development of atherosclerosis in ApoE-deficient mice while the administration of exogenous IL-33 reduces the development of atherosclerosis." (PMID 28611297, 2017). "This might be one reason why Paeonol can restrict atherosclerosis development in apoE-/- mice." (PMID 29354055, 2017). "Furthermore, inhibition of TNF-α reduces atherosclerosis in apolipoprotein E knockout mice." (PMID 28427397, 2017). "To investigate whether macrophagic CD146 is involved in the development of atherosclerosis, we first tested its expression on the macrophage foam cells in atherosclerotic plaques of carotid artery from both human and Western diet-fed ApoE−/− mice, an animal model for atherosclerosis." (PMID 28084332, 2017). "To determine whether a pMAA antigen-based ELISA can detect early increases in anti-MAA antibody titers in atherosclerosis, we next addressed whether serum levels of IgG and IgM antibodies against pMAA are increased at a very early stage of atherosclerosis in ApoE-/- mice fed with a normal diet." (PMID 28222187, 2017). "Thus, through in vivo and in vitro studies, we have demonstrated that the Mas receptor agonist AVE0991 exhibits anti‐inflammatory properties affecting monocyte/macrophage differentiation and recruitment to the perivascular space at early stages of atherosclerosis in ApoE‐/‐ mice." (PMID 27935022, 2017). "Thus, exploring the effect of GTP treatment on the critical regulator of hepatic lipid metabolism in ApoE-knockout mice could further explain the positive effects of GTP against atherosclerosis from the standpoint of lipid homeostasis." (PMID 28777810, 2017). "Likewise, active immunization against specific microbes of gut microbiota has demonstrated to promote an apoE-mediated reduction of circulating levels of proinflammatory cytokines and the impairment of atherosclerosis and western diet-related inflammatory state in general." (PMID 29163168, 2017). "In addition, apoE’s role gains prominence during atherosclerosis, when it participates in reverse cholesterol transport with macrophages secreting large amounts of lipid-free apoE, which in turn promotes cholesterol efflux and formation of high density lipoproteins (HDL) containing apoE." (PMID 28644829, 2017). "Furthermore, there was a significant negative correlation between CD11b and MOMA-2-positive lesion area in ApoE-/- mice, suggesting a possible protective function of CD11b, which is inhibited by Ang-1, thereby resulting in enhanced atherosclerosis in ApoE-/- mice." (PMID 28069704, 2017). "However, the validity of this biomarker remains unclear as treatment with modified CRP and native CRP have been shown to give opposite effects on atherosclerosis in ApoE(−/−) mice." (PMID 28351393, 2017). "APOE was a risk gene for IS, but not independent, especially for large artery atherosclerosis IS." (PMID 29074556, 2017). "Thus, we investigated whether serum levels of IgG and IgM antibodies against M2FA are increased in atherosclerosis-prone ApoE−/− mice fed with a normal diet." (PMID 28883613, 2017). "A recent study demonstrated that apolipoprotein E-deficient (ApoE−/−) mice treated with TSLP developed significantly fewer atherosclerotic plaques in the aortic root compared with controls, along with decreased inflammation in the aorta, indicating a protective role of TSLP in atherosclerosis." (PMID 28615347, 2017). "Therefore, Paeonol treatment restricted atherosclerosis lesion development in apoE-/- mice." (PMID 29354055, 2017).
atherosclerosis (continued). "By contrast, our group has shown that human full-length OPG induced the proliferation of rodent vascular smooth muscle cells and increased atherosclerosis extension in diabetic ApoE-knockout mice, suggesting that this molecule could actually promote atherosclerosis." (PMID 27200369, 2016). "However, ApoE(−/−) mice spontaneously exhibit atherosclerosis." (PMID 27698357, 2016). "However, the roles of both innate and adaptive immune responses were mostly investigated using the ApoE−/− mouse model of atherosclerosis and our results may help to clarify the apparently contrasting results observed." (PMID 27383250, 2016). "To test this hypothesis, we fed apoE knockout (KO) mice, the most popular animal model for human hyperlipidemia and atherosclerosis, with dietary cocoa powder for 12 weeks and compared their lipid profiles, aortic atherosclerosis, and hepatic mRNA expression with those of the control mice." (PMID 26980943, 2016). "In this study, we investigated the effects of DISGT on atherosclerosis-related markers, including intercellular adhesion molecule-1 (ICAM-1), vascular cell adhesion molecule-1 (VCAM-1), and E-selectin, in high-fat diet (HFD)-induced apolipoprotein E-deficient (ApoE−/−) mice." (PMID 27608856, 2016). "The data presented here provide the first evidence that ISL attenuates the development of atherosclerosis and hepatic steatosis in Western diet-fed apoE−/− mice, and the potential mechanism may include amelioration of lipid metabolism, inflammation, and oxidative status." (PMID 27869741, 2016). "The first mouse model with a switched-off gene for apolipoprotein E was generated almost contemporaneously in two laboratories in the United States, and shortly thereafter this model was described as “the best animal model of atherosclerosis” available at that time." (PMID 27618031, 2016). "However, it has not been fully understood whether miR-27 affects the expression of LPL and subsequent development of atherosclerosis in apolipoprotein E knockout (apoE KO) mice." (PMID 27257686, 2016). "Hence, removal of Adamts4 attenuates diet induced atherosclerosis in ApoE−/− mice." (PMID 27491335, 2016). "Therefore, in the current studies we evaluated the development of atherosclerosis in ApoE-/-mice." (PMID 25803585, 2015). "However, if type of SVD is considered (that is, atherosclerosis versus CAA), the direct relationship between MBs and WMHs and AD biomarkers might reflect underlying CAA and AD, driven in common by ApoE ε4 genotype." (PMID 25722748, 2015). "By contrast, a number of studies in ovariectomized female mice showed atheroprotection by testosterone, and similar to our findings, 1 study showed that the nonaromatizable AR agonist DHT protected against atherosclerosis in female apoE-deficient mice, supporting the importance of the AR." (PMID 25550469, 2015). "Indeed, ABA administration has been reported to improve atherosclerosis in ApoE-/- mice." (PMID 26488296, 2015). "To identify genes that are specifically regulated with atherosclerosis progression, we used a whole mouse genome array to profile the gene expression in the thoracic aortas from ApoE−/− mice, comparing older atherosclerotic ApoE−/− mice with young littermate animals before plaque development." (PMID 25782711, 2015). "Therefore, knockdown TLR4 expression attenuated CUMS-induced atherosclerosis maybe though lowering the downstream inflammatory cytokines expression in apoE-/- mice." (PMID 25860573, 2015). "In addition, this model includes the atherosclerosis-prone ApoE-null mouse on a fatty diet." (PMID 26345322, 2015).
atherosclerosis (continued). "To investigate the role of dystrophin in intimal recruitment of smooth muscle cells (SMCs) that maintains plaque stability in atherosclerosis we applied a shear stress-modifying cast around the carotid artery of apolipoprotein E (ApoE)-null mice with and without the mdx mutation." (PMID 26345322, 2015). "In addition, CR reduces atherosclerosis and oxidative stress in the aorta of ApoE−/− mice." (PMID 24834056, 2014). "As a result, we presumed that Nur77 induced reduction of atherosclerosis progression in apoE−/− mice fed a high-fat/high-cholesterol diet might also occur through a pathway where Nur77 might inhibit proliferation of SMCs and thus protected against SMC-rich lesion formation." (PMID 24498071, 2014). "Furthermore, the degree of atherosclerosis in ApoE-deficient mice with SNX was similar in mice with or without overexpression of DDAH1." (PMID 24690995, 2014). "Similarly, isolated ApoE deficiency (ApoE−/−), a model of hyperlipidemia and atherosclerosis, does not impair insulin sensitivity." (PMID 26167199, 2014). "However, the potential of FDG for the non-invasive experimental assessment of atherosclerosis in the widely used apolipoprotein E-deficient (apoE−/−) mouse model of atherosclerosis has not been clearly defined." (PMID 25054923, 2014). "Moreover, genetic ablation of iNOS protected ApoE-null mice from atherosclerosis." (PMID 24587793, 2014). "Knocking-out Arg-II gene in the atherosclerosis-prone ApoE−/− mice (ApoE−/−/Arg-II−/−) decreases inflammatory cytokine levels and macrophage content in the aortas, reduces atherosclerotic plaque formation, and reveals more stable plaque features as compared to ApoE−/−Arg-II+/+ control mice." (PMID 25386179, 2014). "Indeed, atherosclerosis development is diminished in ApoE−/− treated with a BAFFR blocking mAB." (PMID 24478772, 2014). "In addition, overexpression of the ADMA degrading enzyme, DDAH1, in SNX treated ApoE-deficient mice does not ameliorate atherosclerosis." (PMID 24690995, 2014). "Concordantly regulated genes between vitamin E-treated and captopril-treated ApoE−/− mice could be of significant relevance for the pathogenesis of atherosclerosis because more than 82% (i.e., 48) of those commonly regulated probe sets were normalized toward B6 control level." (PMID 23801967, 2013). "However, when fed a high fat, high cholesterol diet containing cholate (HFCC diet), these mice rapidly develop aortic and CA atherosclerosis and cardiac morphological, conductance and functional abnormalities that are strikingly similar to those seen in SR-BI/apoE double KO mice." (PMID 23967310, 2013). "We found that celastrol treatment, 30 days, could reduce atherosclerotic plaque size, consisting with the previous study that celastrol attenuates atherosclerosis in apoE−/− mice by inhibiting inflammation in the arterial wall, but the exact mechanism was not explored." (PMID 23799016, 2013). "Thus, the aorta of atherosclerosis-prone ApoE−/− mice is characterized by a significant down-regulation of neuron-specific genes, which could reflect the development of perivascular nerve degeneration." (PMID 23801967, 2013). "Therefore, we evaluated the effects of niacin without and with simvastatin on atherosclerosis development and investigated the underlying mechanisms and contributing factors in APOE*3Leiden.CETP mice." (PMID 23840481, 2013). "Thus, downregulation of CD36 and upregulation of ABCA1 in macrophages may have contributed to the slower progression of atherosclerosis in the brachiocephalic artery of AdipoR2-/-ApoE-/- mice in the present study." (PMID 24324556, 2013).